ZNF397 (zinc finger protein 397)
Description:
Isoform 3 acts as a DNA-dependent transcriptional repressor.
Synonyms: ZNF47; ZSCAN15; MGC13250
Tractability: Antibody: its Gene Ontology location is reachable by antibodies, with high confidence; the Human Protein Atlas places it where antibodies can reach. PROTAC: UniProt records ubiquitination sites on it; ubiquitination databases record sites on it.
Gene: Protein-coding gene on chromosome 18 (35,240,508 to 35,267,133, forward strand). Ensembl gene ENSG00000186812.
Subcellular location: Nucleus (Isoform 1); Nucleus (Isoform 3); Cytoplasm
Subcellular location (Human Protein Atlas): Cytosol; Nucleoli; Plasma membrane; Microtubules
Gene Ontology:
Molecular function: protein binding; DNA-binding transcription factor activity, RNA polymerase II-specific; RNA polymerase II cis-regulatory region sequence-specific DNA binding
Biological process: regulation of transcription by RNA polymerase II; regulation of DNA-templated transcription
Cellular component: nucleus; cytoplasm
Genetic constraint (gnomAD): Loss-of-function variants: 38 observed, 51.34 expected, observed/expected ratio (o/e) 0.74, 90% interval 0.57 to 0.97. The upper end of that interval is the gene's LOEUF score, 0.97, which puts it in group 4 of 6, group 1 being the genes least tolerant of losing a copy. Missense variants: 624 observed, 627.95 expected, observed/expected ratio (o/e) 0.99, 90% interval 0.93 to 1.06. Synonymous variants: 228 observed, 215.75 expected, observed/expected ratio (o/e) 1.06, 90% interval 0.95 to 1.18.
Homologues: Orthologues: chimpanzee ZNF397 (99% identical), macaque ZNF397 (97% identical), dog ZNF397 (88% identical), pig ZNF397 (87% identical), rabbit ZNF397 (87% identical), guinea pig ZNF397 (85% identical), rat Zfp397 (84% identical), mouse Zfp397 (83% identical). Paralogues in human: ZKSCAN8 (51% identical), ZSCAN12 (45% identical), ZSCAN30 (45% identical), ZKSCAN1 (43% identical), ZNF165 (40% identical), ZKSCAN3 (40% identical), ZSCAN21 (40% identical), ZSCAN31 (40% identical), ZKSCAN4 (39% identical), ZNF394 (38% identical), ZSCAN26 (38% identical), ZNF263 (37% identical), and 18 more.